RN7SL840P (RNA, 7SL, cytoplasmic 840, pseudogene)
Gene: Miscellaneous RNA gene on chromosome 10 (72,582,803 to 72,583,086, forward strand). Ensembl gene ENSG00000272536.
Homologues: Orthologues: chimpanzee Metazoa_SRP (99% identical), macaque Metazoa_SRP (93% identical), rabbit Metazoa_SRP (64% identical). Paralogues in human: RN7SL1 (83% identical), RN7SL3 (83% identical), RN7SL2 (83% identical), RN7SL126P (82% identical), RN7SL147P (81% identical), RN7SL88P (81% identical), RN7SL130P (80% identical), RN7SL242P (80% identical), RN7SL321P (80% identical), RN7SL650P (80% identical), RN7SL7P (80% identical), RN7SL414P (80% identical), and 703 more.